ZEB1 (zinc finger E-box binding homeobox 1)
Diseases named in the same sentence as ZEB1 in open-access papers (continued):
Sharing a sentence is not in itself a finding about the gene and the disease.
breast carcinoma (continued). "In the bone tropic cells, NOG, FST and CHRDL1 are all positively regulated by ZEB1, whereas in different parental breast cancer cell lines only NOG and CHRDL1 are effectively targeted by ZEB1 and an antagonistic regulatory mechanism between NOG and FST seems to dominate and determine FST expression." (PMID 25973542, 2015). "To test for the role of BMP-inhibitor expression by the tumor cells in facilitating this differentiation, we additionally incubated Raw264.7 cells with conditioned media (CM) from various breast cancer cells expressing different levels of ZEB1 and the BMP-inhibitors NOG and FST." (PMID 25973542, 2015). "Additionally, lnc-ATB significantly correlated with the expression of ZNF217 and ZEB1 in the tissues of TR breast cancer patients (P = 0.025 and P < 0.001 respectively)." (PMID 25871474, 2015). "Taken together, these results suggest that these natural compounds could contribute to the prevention of breast cancer via the modulation of the miR-200c/ZEB1/E-cadherin pathway." (PMID 26423775, 2015). "Indeed, miR-200c upregulation after treatment with one of these compounds inhibited ZEB1 expression, resulting in E-cadherin induction and vimentin inhibition in breast cancer cell lines." (PMID 26423775, 2015). "The down-regulation of ZEB1 and ZEB2 increased E-cadherin expression; in contrast, loss of miR-200, which occurs in many different human cancers, including breast cancer, ovarian cancer, prostate cancer, and endometrial carcinoma, results in increased ZEB1/ZEB2 and repression of E-cadherin." (PMID 25367080, 2014). "Notably in this regard, recent studies have shown that MUC1-C induces EMT in breast cancer cells by the upregulation of ZEB1 and the coordinate suppression of miR-200c." (PMID 25245423, 2014). "Recently, Lorenzatti and colleagues found that CCN6, a tumor inhibitory protein, could suppress the expression of EMT transcriptional factor ZEB1 in breast cancer cells through attenuation of IGF-1R signaling." (PMID 23663564, 2013). "Likewise, our studies outline the consequences of ZEB1-mediated gene repression, that is, the suppression of epithelial gene expression and cellular proliferation in breast cancer cells." (PMID 24283570, 2013). "This work identifies ZEB1 as a transcriptional repressor of MYB and suggests a reciprocal MYB-ZEB1 repressive relation, providing a mechanism through which proliferation and the epithelial phenotype may be coordinately modulated in breast cancer cells." (PMID 24283570, 2013). "ZEB1 may also promote metastasis, as shown in a xenograft mouse model and significantly higher ZEB1 expression is seen in human breast cancer cell lines of the more mesenchymal/invasive basal B subgroup." (PMID 24283570, 2013). "In this study, we investigated the expression of zeb1, twist and snail in epithelial tumor and stromal compartments in a large prospective set of breast carcinomas to elucidate whether these factors are important in the spread of breast tumor cells in vivo." (PMID 21324165, 2011). "EMT is the initial stage in cancer metastasis, and the EMT activator Zeb1 has been identified as a key factor in promoting metastasis formation in various types of cancer, including hepatocellular carcinoma and pancreatic, prostate, colorectal, and breast cancers." (PMID 40806166, 2025). "In addition, the existence of the ZEB1/KLF5-mTOR-CCND1/ABCB1 axis may be involved in the paclitaxel response pathway, and it is influencing the susceptibility and prognosis of breast cancer." (PMID 38164285, 2024). "In breast cancer, there may be such a negative regulatory loop between ZEB1 and NOTCH." (PMID 38164285, 2024). "Interestingly, it has been reported that miR-142-3p could affect progression of breast cancer by directly targeting ZEB1." (PMID 37403081, 2023).
breast carcinoma (continued). "Similarly, it remains unclear why shRNA-mediated knockdown of ZEB1 in the MDA-MB-231 breast cancer cells was correlated with elevated miRNA-200c-3p levels although the MDA-MB-231 cells express ZEB2 too." (PMID 38139138, 2023). "Interestingly, while the fractions of the ALDH1-positive cells were comparable between the HS578T-Hyg breast cancer cells, the M13HS-8 tumor hybrids and their ZEB1-KO variants, the ALDH1-positive cells (27.3 ± 4.0%) were highly enriched in the M13HS-2 ZEB1-KO cells." (PMID 38139138, 2023). "Results of recent studies have shown that ZEB1 and ZEB2 are associate with the response to radiotherapy and chemotherapy of several cancers, such as pancreatic carcinoma, head and neck squamous carcinoma, squamous carcinoma, breast cancer, non-small cell lung, and bladder carcinoma." (PMID 37636389, 2023). "Our previous studies indicated that ZEB1 could repress multiple miRNAs in breast cancer." (PMID 36100877, 2022). "Similarly, another study also reported that TTN-AS1 could promote the growth of breast cancer cells by targeting the miR-139-5p/zinc finger E-box binding homeobox 1 (ZEB1) axis." (PMID 36613528, 2022). "Therefore, during the early stages of EMT, ZEB1 activation in ERα+ breast cancer cells stimulates the expression of markers of partial EMT, which may impact growth and tissue tropism during the metastatic process." (PMID 35440541, 2022). "Overall, these findings suggest that CD151 dependency is associated with the ZEB1+/ERα+ status and that CD151 could be a promising target for inhibiting cell proliferation, migration, and invasion during partial EMT induced by ZEB1 in ERα+ breast cancer." (PMID 35440541, 2022). "Additionally, SLC3A2 was a target gene of ZEB1 in breast cancer chemoresistance, it maybe the chemotherapy of laryngeal carcinoma is associsated with the result of high SLC3A2 patients with longer survival." (PMID 35057861, 2022). "In addition to the ERK pathway, ZEB1/2 could be regulated by NF-κB signaling pathways, as the basal-like subtype of breast cancer cells exhibits elevated NF-κB activity more than the luminal subtype." (PMID 36140527, 2022). "In addition, it has been found that exogenous ZEB1 expression can induce the acquisition of stem cell characteristics in breast cancer through the ZEB1/Ngn3 axis and that high ZEB1 expression predicts radiotherapy relapse in triple-negative breast cancer, which is usually enriched in CSCs." (PMID 35404029, 2022). "Moreover, ginkgolide B could decrease the invalidity of breast cancer by suppressing the translation of zinc finger E-Box binding homeobox 1 (ZEB1) protein." (PMID 35630688, 2022). "As a transcriptional regulator containing multiple functional domains, ZEB1 can participate in the regulation of the expression of various oncogenes, including hTERT; for example, ZEB1 can promote the occurrence and development of breast cancer by upregulating the expression of hTERT." (PMID 35739589, 2022). "Moreover, the up-regulated miR-205 can also target ZEB1 to inhibit breast cancer cell invasion." (PMID 33428601, 2021). "Moreover, ZEB1 is abnormally expressed in different types of tumors, including cervical cancer, pancreatic cancer, osteosarcoma, lung cancer, liver cancer, gastric cancer, colorectal cancer, and breast cancer." (PMID 33391437, 2021). "Accordingly, the expression of transcriptional repressors of E-Cadherin, including zinc finger E-box-binding homeobox 1 (ZEB1), zinc finger E-box-binding homeobox 2 (ZEB2), twist-related protein (Twist), zinc finger protein, Snail, and Slug, is associated with poor prognosis in breast carcinoma." (PMID 33626096, 2021). "Additionally, we examined whether Zeb1 depletion in breast cancer cells would impair their interaction with endothelial cells." (PMID 33046710, 2020).
breast carcinoma (continued). "Finally, the results revealed that MEK1 inhibitor (when combined with radiation) significantly reduces the migratory potential of MDA-MB-231 breast cancer cells including reduction of miR-221 expression and corresponding downstream ZEB1 and uPAR (EMT) marker expression." (PMID 33327491, 2020). "Interestingly, ZEB1 directly represses the ESRP1 locus in breast cancer cells." (PMID 32005677, 2020). "However, the microenvironmental cues that are responsible for the aberrant expression of Zeb1 in breast cancer remain largely unknown." (PMID 33046710, 2020). "Notably, ZEB1 has been identified as a key player in migration of breast cancer cells." (PMID 32664703, 2020). "Furthermore, M3 genes have a significant association with the prognosis of breast cancer, indicating that genes that are controlled by ZEB1 but not other TGF-β-dependent pathways likely play a protective role." (PMID 31275609, 2019). "However, whether ZEB1 expression is involved in the response to neoadjuvant chemotherapy in breast cancer has yet to be determined." (PMID 30976202, 2019). "In addition, upregulation of ZEB1 was observed in invasive ductal and lobular breast cancer." (PMID 31744193, 2019). "Therefore, the downregulation of IRF6 in GC or in EMT process of GC, SCC and breast cancer may be due to upregulation of ZEB1." (PMID 31019894, 2019). "In conclusion, we speculate that ZEB2 and ZEB1 may have subtly different roles in breast cancer metastasis and that the current models of cancer progression may not reflect the complexity and hierarchy of the network of interactions that orchestrate these programmes." (PMID 29963231, 2018). "Because ZEB1 functions as a DNA-binding protein with an essential role in breast cancer development, we performed chromatin immunoprecipitation (ChIP) coupled deep DNA sequencing (ChIP-seq) to identify endogenous transcriptional targets of ZEB1 in MDA-MB-231 cells." (PMID 29352223, 2018). "Taken together with our observations that ZEB1 overexpression decreases breast cancer cell sensitivity to EPI and ETOP treatment in an ATM-dependent fashion, ATM upregulation may at least partially account for the resistance of this subset of breast cancers against chemotherapy." (PMID 29352223, 2018). "Thus, dysregulation of Ngn3 may provide a mechanistic link between the ectopic expression of ZEB1 and the ontogeny of aggressive breast cancer." (PMID 28903350, 2017). "Therefore, our study indicates that ZEB1 may act as a determinant of antiestrogen resistance in breast cancer." (PMID 28383555, 2017). "To determine whether ZEB1-regulated ER-α expression in breast cancer is correlated with DNA methylation, we performed a search using the CpG island prediction database MethPrime and identified an upstream CpG-rich region at position −4138/−3872 of the ER-α promoter." (PMID 28383555, 2017). "Furthermore, transcription factor ZEB1 can inhibit the expression of cell polarity gene lethal giant larvae homolog 2 (Lgl2), which is critical for maintenance of epithelial cell phenotype and is often down-regulated in breast cancer." (PMID 28356139, 2017). "In this study, we found that AESN could attenuate N-cadherin, vimentin, and ZEB1 levels of MCF-7 breast cancer cells after 24 h treatment, revealing that AESN may demonstrate chemotherapy resistance, metastasis, and cancer cell migration as well as suppress cancer cell proliferation." (PMID 27136519, 2016). "This suggests ZEB1 expression may play a crucial role in PB resistance in TN breast cancers." (PMID 26646320, 2016). "Polycomb-mediated regulation of the ZEB1 promoter has been recently implicated in the conversion of breast cancer non-stem to stem cells and loss of H3K27me3 at the poised promoter of ZEB1 was functionally linked to activation of the stemness regulatory transcriptional machinery." (PMID 27563817, 2016). "ZEB1 is one candidate that may affect breast cancer in this way." (PMID 26646320, 2016).
breast carcinoma (continued). "Interestingly, ZEB1 has higher expression in basal-like breast cancer than luminal breast cancer." (PMID 27815674, 2016). "Lnc-ATB may be function as a ceRNA to up-regulate the ZEB1 expression in breast cancer." (PMID 25871474, 2015). "In future studies, it will be also important to determine whether PIAS1 function intersects with other regulators of breast cancer metastasis including the transcriptional regulators Zeb1/2 and Twist, which are both induced by TGFβ signaling and promote tumor metastasis." (PMID 25594015, 2014). "Zeb1/δEF1 is a predictor of poor prognosis of uterine cancer and is expressed in colorectal cancer, however a statistical correlation of Zeb1/δEF1 with breast cancer progression has not been reported, despite an association of its' histological expression with increasing breast tumour grade." (PMID 19604397, 2009). "After ZEB1 overexpression, the EMT pathway of BT549 and MB231 breast cancer cells was up-regulated, as shown by the increase in N-cadherin and Vimentin expression." (PMID 41158758, 2026). "Overall, these anti-VM miRNAs interfere with multiple oncogenic pathways, including IL-6/STAT3, AXL, ZEB1, and HIF-1α, underscoring the multifaceted regulatory landscape of miRNA-mediated VM control in breast cancer." (PMID 41400702, 2025). "ZEB1 acts as an interactive partner with AP-1 to form a transactivation complex with YAP and stimulate aggressive claudin-low subtype of breast cancer." (PMID 39858015, 2025). "ZEB1 forms complexes with YAP and AP-1 (FOSL1/JUN), activating tumor-promoting genes and reinforcing EMT, particularly in aggressive claudin-low breast cancer subtypes." (PMID 40572800, 2025). "In breast cancer, PRMT1 promotes ZEB1 transcription via H4R3me2a, facilitating cell migration and invasion." (PMID 41204384, 2025). "ZEB1 and ZEB2 have been experimentally shown to promote cell migration and invasion in breast cancer and pancreatic cancer." (PMID 40830747, 2025). "Another overexpressed in breast cancer lncRNA is ROR that induces EMT by inhibiting miR-205 activity, hence preventing degradation of genes such as N-cadherin, vimentin, and ZEB1." (PMID 39912983, 2025). "This agrees with data in breast cancer identifying ZEB2 as being important for tumor cell migration and invasion and ZEB1 being more important for tumor cell growth/colony formation." (PMID 40736379, 2025). "Transformed cells producing a high ectopic expression of ZEB1 generate lactate, which activates the PKA/CREB signaling cascade and results in the phenotype of alternatively activated (M2) macrophages in breast cancer." (PMID 39858015, 2025). "In lung adenocarcinoma and breast cancer, CDK4/6-mediated phosphorylation and activation of USP51 is essential for deubiquitinating and stabilizing ZEB1, thereby promoting cancer metastasis." (PMID 40307228, 2025). "In breast cancer, PRMT1 promotes EMT by activating ZEB1 transcription via H4R3me2a modification, whereas PRMT1 silencing induces G1 arrest and cellular senescence." (PMID 41204384, 2025). "Another lncRNA, MIR497HG, is suppressed by ZEB1-mediated recruitment of DNMT3B and HDAC1/2 in endocrine-resistant breast cancer; meanwhile, ERα enhances its expression in sensitive conditions, affecting the PI3K/Akt pathway via miR-195/497." (PMID 40843360, 2025). "Our preliminary results showed the opposite expression pattern of NOTCH3 and ZEB1 in breast cancer, which predicts a potential regulatory axis between NOTCH3 and ZEB1." (PMID 38164285, 2024). "In contrast, in luminal-type breast cancer cells, which are unresponsive to EMT-inducing signals, the Zeb1 promoter is marked only by H3K27me3, locking the promoter in a repressed state." (PMID 38385532, 2024). "It is well known that NF-κB/ZEB-1 is involved in cancer invasion in various tumours, including the process of EMT in breast cancer." (PMID 38594707, 2024).
breast carcinoma (continued). "In order to further explore the expression pattern of NOTCH3 and ZEB1 in breast cancer, online databases CCLE and THPA were mined to analyze the expression of NOTCH3 and ZEB1 in different breast cancer cell lines." (PMID 38164285, 2024). "Our findings provide evidence for the combined role of ZEB1 and ZEB2 in the acquisition of the EMT phenotype in primary breast cancer." (PMID 39256881, 2024). "MiR-205 is well-established as a tumor suppressor in multiple cancer types including in breast cancer, regulating key EMT factors including ZEB1/2." (PMID 39327614, 2024). "According to the hierarchical clustering analysis of 52 breast cancer cell lines, SOD2 and GPX8 genes were part of the mesenchymal gene signature and co-clustered with ZEB1, VIM, and SNAI2." (PMID 38172210, 2024). "In patients with breast cancer, the level of NOTCH3/miR-223/ZEB1 was analyzed and their prognostic value determined." (PMID 38164285, 2024). "In a study on breast cancer, ALA-treated MDA-MB-231 and 4T1 breast cancer cell lines both exhibited downregulated expression of EMT markers such as Snail, vimentin, and Zeb1, along with impaired cell migration capabilities." (PMID 39199143, 2024). "Among various types of cancers, human breast cancer cells and human HNSCC cells have been well characterized in EMT studies, and show a positive correlation between the expression of ZEB1/2 (ZEB1 and ZEB2) and aggressive cancer cell phenotypes." (PMID 39362647, 2024). "Alternatively, the transcription factor Zinc-finger E-box-binding homeobox 1 (ZEB1) facilitates EMT and is crucial for breast cancer invasion and metastasis." (PMID 39660126, 2024). "In breast cancer cells, miR-708-3p inhibits EMT by directly targeting ZEB1, cadherin 2, and vimentin." (PMID 38920689, 2024). "A few studies have implicated a prognostic role for EMT-related transcription factors ZEB1 and ZEB2 in tumor types, such as ovarian, colorectal, and breast carcinomas." (PMID 38719798, 2024). "Our research investigated the impact of miR-561-3p on the expression of ZEB1, HIF1A and MYC in breast cancer cells for the first time." (PMID 38462658, 2024). "The inhibition of CAF-induced expression of OPN or ZEB1 in breast cancer cells confirms the antitumoral activities of calcitriol in CAFs because OPN and ZEB1 are involved in various processes leading to breast tumor progression." (PMID 38360633, 2024). "Breast cancer patients with high expression of NOTCH3 tended to have long DRFS (p = 0.236, HR = 0.583), while high ZEB1 levels predicted poor DRFS in patients with breast cancer (p = 0.0151, HR = 2.59)." (PMID 38164285, 2024). "FTO promotes the stability and expression of ZEB1 transcripts by decreasing m6A RNA methylation, leading to chemoresistance and epithelial-mesenchymal transition (EMT) of breast cancer cells." (PMID 38782769, 2024). "The HS578T-Hyg breast cancer cells and M13HS-2 and -8 tumor hybrids were ZEB1 positive, which was in line with low levels of the miRNA-200c-3p in these cells." (PMID 38139138, 2023). "Several transcriptional activators have been identified to regulate hTERT expression in breast cancer cells, including c-MYC, STAT3, NF-κB, ETS2, ERα, Sp1, KLF4, and ZEB1/YAP, among others." (PMID 37612721, 2023). "A protein assessment by Western blot analysis confirmed the detection of ZEB1 in Esc-Inf cells, though the protein level remained low compared to EMT-committed Hs578T breast cancer cells." (PMID 36765930, 2023). "ZEB1-KO resulted in rather unexpected results, since both miRNA-200c-3p levels and CDH1 expression levels remained unchanged in the HS578T-Hyg ZEB1-KO breast cancer cells and M13HS ZEB1-KO tumor hybrids." (PMID 38139138, 2023). "Although one study examined the expression of ZEB1 and ZEB2 in five canine mammary carcinoma cell lines, to the best of our knowledge, ZEB mRNA expression has never been studied in CMT and FMT tissues." (PMID 36899736, 2023).